LCT (lactase)
Diseases named in the same sentence as LCT in open-access papers (continued):
Sharing a sentence is not in itself a finding about the gene and the disease.
prostate carcinoma (8 papers, 2013 to 2024). A carcinoma that arises from epithelial cells of the prostate gland. "An omnibus analysis via a class-based association test (GenCAT) was conducted to determine if the lactase persistence haplotype block was associated with prostate cancer risk." (PMID 33193640, 2020). "Based on the function of the genes and microRNA, we studied health phenotypes likely to be impacted by the lactase persistence allele: prostate cancer status, cardiovascular disease status, and bone mineral density." (PMID 33193640, 2020). "We investigated common genetic variation in the lactase gene in relation to intake of dairy products and risk for prostate cancer in a large, European study (EPIC)." (PMID 22965418, 2013). "In participants with prostate cancer, the frequency of the lactase T allele was 40% and in control participants it was 40.5%." (PMID 22965418, 2013). "The C/T-13910 lactase variant (rs4988235) was genotyped in 630 men with prostate cancer and 873 matched control participants." (PMID 22965418, 2013). "However, a recent Mendelian randomisation study found only limited evidence for an association between genetically determined higher milk intake (proxied through a genetic variant associated with lactase persistence in adulthood) and risk of prostate cancer." (PMID 38643440, 2024). "We used summary statistics from large genome-wide metanalyses—32,965 bone mineral density, 140,306 prostate cancer and 184,305 coronary artery disease subjects—to evaluate whether the lactase persistence allele was associated with these disease phenotypes." (PMID 33193640, 2020). "If there is a threshold effect of milk consumption on prostate cancer risk, an association between the lactase persistence variant and prostate cancer might only be seen in populations with high milk consumption." (PMID 33261611, 2020). "We investigated the association of the European lactase persistence haplotype block with prostate cancer risk using genome-wide meta-analysis statistics of prostate cancer from 79,194 prostate cancer cases and 61,112 controls of the PRATICAL Consortium Oncoarray database." (PMID 33193640, 2020). "Odds ratios (ORs) for prostate cancer in relation to lactase genotype were estimated by conditional logistic regression." (PMID 22965418, 2013). "The current study was nested in EPIC, and results from this first Europe-wide study suggest that while the C/T13910 lactase polymorphism is associated with milk intake, the variant has no large effect on prostate cancer risk." (PMID 22965418, 2013). "Thus, despite recent selection for the lactase persistence allele there is little evidence that the LP haplotype block is associated with bone mineral density nor the risk of prostate cancer or coronary heart disease." (PMID 33193640, 2020). "To further examine this possible relationship, we investigated the hypothesis that a genetic polymorphism in the lactase (LCT) gene might be associated with elevated dairy product intake and increased prostate cancer risk in a case–control study nested in EPIC." (PMID 22965418, 2013). "Finally, we will review the literature focusing on the lactase persistence/non-persistence populations as a comparative model in order to determine the protective or adverse effects of milk and dairy foods on the incidence of colorectal, ovarian and prostate cancers." (PMID 26343715, 2015).
colorectal cancer (7 papers, 2008 to 2026). A primary or metastatic malignant neoplasm that affects the colon or rectum. "The impact of adult lactase deficiency and continued dairy consumption on the microbiome, and its contribution to colorectal cancer reduction, is highlighted." (PMID 41756623, 2026). "Lactase-phlorizin hydrolase was researched to be associated with colorectal cancer patients by Piepoli A." (PMID 32489319, 2020). "A genome-wide association study found that lactase gene locus was associated with Bifidobacterium abundance and the colonization of Bifidobacterium animalis markedly reduces the polyp burden and possibly the risk of colorectal cancer." (PMID 36424608, 2022).
diabetes (7 papers, 2016 to 2025). "The index phenotypes we analyzed were, in order of presumed increasing genetic complexity, lactase persistence, melanoma, and Type 2 diabetes mellitus/fasting glucose." (PMID 27042214, 2016). "Where lactase persistence did not emerge, birth weight was constrained at lower levels, and this contributes to contemporary variability in diabetes risk." (PMID 34497534, 2021). "We examined three disease phenotypes, lactase persistence, melanoma, and Type 2 diabetes mellitus." (PMID 27042214, 2016). "We therefore aimed to define 1) the prevalence of lactase non-persistence among individuals with diabetes and non-diabetes in Thai population and 2) the links between lactase non-persistence, milk consumption, and risk of diabetes mellitus." (PMID 37585412, 2023). "Furthermore, HT reduced the rise in intestinal enzymes (lactase, sucrose, and maltase) brought on by STZ, frequently increasing diabetes." (PMID 39940428, 2025).
Allergy (6 papers, 2015 to 2024). An allergy is an immune response or reaction to substances that are usually not harmful. "Whilst this may lead to changes in the immune system which reduce the risk of IgE-mediated allergy this altered gut flora can adversely affect digestive enzyme activity, particularly of lactase." (PMID 26816616, 2015).
malnutrition (6 papers, 2011 to 2024). Inadequate nutrition resulting from poor diet, malabsorption, or abnormal nutrient distribution. "Lactose is the major source of dietary carbohydrate during infancy; therefore, the effect of malnutrition on mucosal lactase specific activity is of particular importance during this time period." (PMID 21695035, 2011). "A direct correlation between malnutrition severity and the magnitude of decrease in lactase, and maltase activities has been reported." (PMID 21695035, 2011). "A significant reduction in lactase activity in patients with malnutrition has been reported." (PMID 21695035, 2011). "Two studies compared lactose-free to lactose-containing liquid feeds among children with persistent diarrhea and without severe malnutrition: one compared lactase-treated milk with regular milk and the other compared lactose-free semi-elemental formulas to regular milk." (PMID 24564685, 2013).
diarrhoea (5 papers, 2018 to 2024). "If lactose is not absorbed, due to lactase deficiency, this reaches the colon, where it may cause bloating and/or diarrhoea." (PMID 33806061, 2021).
gastroenteritis (5 papers, 2010 to 2025). An inflammatory disorder that affects the upper and lower gastrointestinal tract. "It accompanies gastroenteritis of various etiologies, as these conditions often reduce the activity of the lactase enzyme thereby impairing the digestion of lactose." (PMID 40004050, 2025). "Mucosal damage in the small intestine caused by GI conditions (e.g., gastroenteritis, short bowel syndrome, GI surgery, drugs, celiac and tropical sprue) may reduce DAO and lactase activity, respectively." (PMID 28042564, 2016). "In addition it should be noted that while in most cases the presence/absence of intestinal lactase in an adult is likely to be genetically determined, the loss of lactase can also be caused by gut trauma such as gastroenteritis." (PMID 20144208, 2010).
Crohn disease (4 papers, 2010 to 2022). A gastrointestinal disorder characterized by chronic inflammation involving all layers of the intestinal wall, noncaseating granulomas affecting the intestinal wall and regional lymph nodes, and transmural fibrosis. "The aim of this study was to determine whether lactase persistence as evident by the T allele of rs4988235 is associated with Crohn's Disease (CD) in a New Zealand population." (PMID 21167073, 2010).
gastrointestinal infections (4 papers, 2014 to 2019). "On the other hand, transient lactase deficiency secondary to brush border damage from gastrointestinal infections is a well-recognized clinical entity that prolongs diarrheal symptoms in the aftermath of acute infections." (PMID 25095704, 2014). "Only when they have no or low lactase expression due to congenital lactase deficiency, gastrointestinal infections, or to preterm birth, can the digestion of lactose be compromised." (PMID 31718111, 2019).
irritable bowel syndrome (4 papers, 2009 to 2023). Irritable bowel syndrome (IBS) is a chronic functional condition of the lower gastrointestinal (GI) tract characterized by abdominal pain or discomfort and disordered bowel habit (diarrhea, constipation, or fluctuation between the two). "A group of Austrian researchers found that the mucosal damage caused by gastroenteritis, irritable bowel syndrome (IBS), short bowel syndrome or gastrointestinal surgery led to a concomitant decrease in DAO and lactase activities." (PMID 35565742, 2022). "However, to date, the effects of lactase deficiency on symptoms of irritable bowel syndrome (IBS) are still not well defined." (PMID 36832931, 2023). "Genetic variants in the OXT promoter region, and in the OXTR gene in DNA samples from 131 rigorously evaluated patients with Irritable Bowel Syndrome (IBS), 408 homozygous subjects referred for lactase (LCT-13910 C>T, rs4988235) genotyping, and 299 asymptomatic blood donors were compared." (PMID 19943975, 2009). "Depending on the ingested quantity of lactose and the activity of the gastrointestinal (GI) mucosal enzyme lactase, patients with LIT may experience symptoms on the irritable bowel syndrome (IBS) spectrum." (PMID 35631167, 2022).
functional dyspepsia (3 papers, 2018 to 2021). "Our results showed that functional dyspepsia patients with ATH hadhigher bloating scores in comparison to those with lactase persistence." (PMID 29384557, 2018). "Of 404 patients with functional dyspepsia and positive for H. pylori whowere included in the HEROES Trial (Mazzoleni etal., 2011), 197 consented to participate in this nested studyaiming the analysis of the lactase gene polymorphism." (PMID 29384557, 2018). "This lack of correspondence is highest in patients with functional gastrointestinal problems, i.e., IBS and functional dyspepsia, as demonstrated by the very high frequency of SRMI in European patients with IBS and the low rate of genetic/genetically determined lactase non-persistence." (PMID 34836089, 2021).
maltase deficiency (3 papers, 2012 to 2018). "Individuals with CoeD frequently have a transient disaccharidase lactase deficiency; however, less was known regarding disaccharidase maltase deficiency in this population." (PMID 27525027, 2016). "Finally, a larger metanalysis of 30 pediatric studies examining 34,753 disaccharide assays found the proportion of lactase deficiency to be 39.2%, maltase deficiency 12.6%, sucrase deficiency 9.0%, and palatinase (isomaltase) deficiency 9.1%." (PMID 30501067, 2018).
necrotizing enterocolitis (3 papers, 2021 to 2022). Necrotizing enterocolitis (NEC) is a devastating disease that affects mostly the intestine of premature infants. "Enteral feeding intolerance is very common in preterm infants and can be a sign of reduced gastrointestinal motility due to the insufficiency of insufficient mature enzymatic system (lactase, lipase, enterokinase, etc.)or may be the initial manifestation of the necrotizing enterocolitis (NEC)." (PMID 35892079, 2022). "Gut structure, function and necrotizing enterocolitis (NEC) incidence were similar between groups, but intestinal weight (−3%) and brush-border enzyme activities were reduced at day 5 (lactase, DPP IV, −8%) in males." (PMID 33643975, 2021).
acne (2 papers, 2018). An inflammatory process of the sebaceous glands which is characterized by comedones, nodules, papules and/or pustules on the skin. "The unadjusted odds ratio for acne in individuals with the lactase persistent genotypes TC/TT vs. the lactase non-persistent genotype CC was 0.84 (0.43:1.62) in the age group 20–39 years, and 0.99 (0.52–1.88) above 40 years." (PMID 30096803, 2018). "How the age of weaning of the lactase enzyme activity impacts acne development is not known." (PMID 30096883, 2018). "In this study, we used the Mendelian randomization design to investigate the long-term effect of milk intake on acne using the lactase persistent (TT + TC)/non-persistent(CC) LCT-13910 C/T genotype in 20,416 adult individuals from The Danish General Population study (GESUS)." (PMID 30096803, 2018).
breast carcinoma (2 papers, 2023 to 2024). "Other examples of polymorphism include Lactase-phlorizin hydrolase gene (LPH) polymorphism, glutathione peroxide gene polymorphism, Manganese superoxide dismutase (MnSOD) in which substitution or deletion of the specific genes resulted in an increased risk of liver and breast cancer, respectively." (PMID 39183982, 2024).
colitis (2 papers, 2018 to 2020). Inflammation of the colon. "Only LCT (Lactase) was dysregulated in active UC with left-sided colitis (log2 fold-change = −5.3, p = 2.25 × 10−2)." (PMID 32731480, 2020). "The debilitating effects of experimental colitis as observed through a significant decrease in intestinal disaccharidases (sucrase and lactase) were evident in Se-Def and Se-Ade groups compared to Se-Sup groups in both homogenate and BBM preparations of colons." (PMID 30063735, 2018).
enteropathy (2 papers, 2017 to 2021). "The majority of infants with CMA can tolerate lactose, except when an enteropathy with secondary lactase deficiency is present." (PMID 29270244, 2017). "There are marked histopathological abnormalities in children with stunting and enteropathy but we cannot exclude the possibility that age-related changes in transcription may be reflected in these data, just as observed for lactase expression." (PMID 34333236, 2021).
giardiasis (2 papers, 2017 to 2019). An infection of the small intestine caused by the flagellated protozoan giardia lamblia. "The association between giardiasis and a decrease in disaccharidase activity (lactase) had already been cited previously, but this effect of parasitization on the absorption of monosaccharaides, fructose in particular, has, so far, not been studied or cited." (PMID 31817420, 2019).
Hyperglycemia (2 papers, 2021 to 2022). An increased concentration of glucose in the blood. "Studies have indicated that quercetin can enhance the tolerance of diabetic animals to hyperglycemia and control the further development of diabetic complications by regulating the activity of lactase in the intestine of diabetic rats." (PMID 34354757, 2021). "In this study, the alpha-glucosidase activity (maltase, sucrase, and lactase) decreased after COS treatment, indicating that COS slowed down carbohydrate decomposition and reduced postprandial hyperglycemia." (PMID 38647883, 2022).
iron deficiency (2 papers, 2023 to 2025). "The disaccharide enzymes, such as sucrase and lactase are involved in carbohydrate digestion and their activities will reduce during iron deficiency." (PMID 37420289, 2023).
melanoma (2 papers, 2016 to 2021). A malignant, usually aggressive tumor composed of atypical, neoplastic melanocytes. "About 40 genes have been associated with melanoma, according to HuGE Navigator, making it substantially more complex than lactase persistence." (PMID 27042214, 2016). "We applied a population-specific PRS (psPRS) to 26 populations from the 1000 Genomes to four phenotypes: lactase persistence (LP), melanoma, multiple sclerosis (MS) and height." (PMID 34903281, 2021).
plague (2 papers, 2014 to 2022). Plague is a severe bacterial infection caused by the gram-negative bacterium Yersinia pestis. "Variants for lactase persistence, eye and hair pigmentation, and (putatively) plague risk had similar allele frequency between EAJ and MAJ (section 15)." (PMID 36455558, 2022).
Rotavirus infection (2 papers, 2022 to 2025). Infection with any of the rotaviruses. "Under normalcy, healthy enterocytes secrete lactase into the small intestine that helps in lactose metabolism, but children with rotavirus infection are unable to tolerate milk due to lactase deficiency that can last for several weeks." (PMID 35632617, 2022). "Galactose can be a derivative of the breaking down of lactose, and rotavirus infection can decrease the production of the enzyme lactase, which is responsible for the digestion of lactose, leading to diarrhea." (PMID 40430193, 2025).
adenoma (1 paper, 2019). A neoplasm arising from the epithelium. "In adenoma-normal, downregulation of DEGs involved in metabolism of brush border proteins (LCT), lipids (APOB/A4), reactive oxygen species (GSTA2), and retinol (RBP2) was observed." (PMID 31211760, 2019).
age-related macular degeneration (1 paper, 2024). Age-related loss of vision in the central portion of the retina (macula), secondary to retinal degeneration. "Five of these proteins (protein-coding genes ECI1, LCT, and NPTXR for glaucoma, WARS1 for age-related macular degeneration (AMD), and SIGLEC14 for diabetic retinopathy (DR)) are newly reported." (PMID 39408566, 2024).
AIDS (1 paper, 2016). A syndrome resulting from the acquired deficiency of cellular immunity caused by the human immunodeficiency virus (HIV). "In contrast to healthy HIV-positive individuals, severe SI and lactase-phlorizin hydrolase deficiencies are identified in most of the jejunal specimens from patients with acquired immune deficiency syndrome (AIDS)." (PMID 26812950, 2016).
asthma (1 paper, 2021). "Previous studies have shown that lactate is a biomarker of exacerbations, and that serum lactase is upregulated during acute asthma treatment, hinting towards early onset or susceptibility to lung disease." (PMID 34834499, 2021).
autism spectrum disorder (1 paper, 2014). A spectrum of developmental disorders that includes autism, and Asperger syndrome. "The synergistic effects of genes and the environment on health are explored in three case studies: adult lactase persistence, autism spectrum disorders, and the metabolic syndrome, providing examples of the interactive complexities underlying these phenotypes." (PMID 25221564, 2014).
cystic fibrosis (1 paper, 2019). Autosomal recessive disorder caused by pathogenic variants in the CFTR gene (cystic fibrosis transmembrane conductance regulator), which encodes a chloride and bicarbonate channel expressed in epithelial cells, and follow the diagnosis criteria. "Cystic fibrosis, which is highly deleterious in its homozygous state, nonetheless confers a positive selective advantage on heterozygous individuals, while lactase persistence seems to be advantageous in both states." (PMID 31316137, 2019).
duodenitis (1 paper, 2020). Acute or chronic inflammation of the duodenum. "Although it is known that cow’s milk allergy can cause duodenitis, lactase deficiency has not been reported to be associated with duodenitis." (PMID 33036568, 2020).
galactose intolerance (1 paper, 2024). "The data sheet of FILGO and TOFA suggests that patients with rare hereditary problems of galactose intolerance, total lactase deficiency or glucose-galactose malabsorption should avoid their use." (PMID 38979406, 2024).
glaucoma (1 paper, 2024). Increased pressure in the eyeball due to obstruction of the outflow of aqueous humor. "A total of 11 unique protein-coding genes posterior probability (PP) of H4 > 0.70 finally remained, including GSTM3 for senile cataract, WARS1, C3, IGFBP7, and PILRA for AMD, ECI1, LCT, and NPTXR for glaucoma, EFEMP1 for myopia, and SIRPG and SIGLEC14 for DR." (PMID 39408566, 2024).
Hypercholesterolemia (1 paper, 2012). An increased concentration of cholesterol in the blood. "It is quite reasonable that, in a time span similar to that which conferred lactase persistence in Europeans, selection pressure in the Maasai from such a diet might result in genetic adaptations against diseases such as hypercholesterolemia and atherosclerosis." (PMID 23028602, 2012).